MMP9 (matrix metallopeptidase 9)
Diseases named in the same sentence as MMP9 in open-access papers (continued):
Sharing a sentence is not in itself a finding about the gene and the disease.
liver fibrosis (continued). "Another study in mouse models of liver fibrosis demonstrated that the resolution is delayed by KC depletion and accelerated by an adoptive transfer of KCs from wild-type animals, compared to KCs from MMP9–/– mice, suggesting that KC-derived MMP9 is essential in resolving fibrosis." (PMID 39063116, 2024). "Subsequently, transcript levels of genes associated with hepatic fibrosis were assessed via qRT-PCR, which revealed a significant upregulation of fibrosis-related transcripts encoding proteins such as procollagen α1(I), TIMP-1, α-SMA (ACTA2), MMP-2, and MMP-9 in the livers of scurfy mice." (PMID 37818371, 2023). "In addition, MMP-9 contributes to resolution of liver fibrosis by promoting HSCs apoptosis." (PMID 35625467, 2022). "Decreases ALT, AST and ALP levels; down-regulates α-SMA, type I collagen, fibrotic factor-CTGF, MMP2 and MMP9; inhibits the activation of the transforming growth factor-β-1/Smad pathway and hepatic stellate cells mediated by transforming growth factor-β1; and prevents liver fibrosis." (PMID 35566359, 2022). "Our study demonstrated ERK2 signaling could regulate MMP9 expression in liver fibrosis mouse model." (PMID 32471201, 2020). "In addition, we and others previously demonstrated that liver MMP-9 expression increases via mesenchymal stem cells’ paracrine effect and might be a protective factor during liver fibrosis." (PMID 30875826, 2019). "It tells us that MMP9 may play a role in the progression of liver fibrosis." (PMID 27907201, 2016). "Thus, the imbalance that favors MMP9 by PZQ treatment is helpful to reverse hepatic fibrosis." (PMID 21629648, 2011). "Investigation of the pathophysiology of the generation of MMP9-expressing hepatoblast-like cells from ES cells and liver resident cells in CCl4-injured livers may lead to discovery of a new treatment approach for liver fibrosis." (PMID 19134049, 2008). "As compared to the control animals, the group treated with methotrexate alone had shown strong evidence of hepatic fibrosis as proven by the significant increase in the hepatic tissue content of hydroxyproline, MMP-3, and MMP-9." (PMID 40143135, 2025). "In TAA-induced liver fibrosis, quercetin decreased liver fibrosis index via provoking HSC apoptosis, and down-expression of MMP-9 and MMP-2." (PMID 40892759, 2025). "Existing research has demonstrated that changes in the secretion levels of IV Col and HA, as well as the gene expression of MMP2 and MMP9 in BRL-3A cells, can reflect liver fibrosis in the body to a certain extent." (PMID 40667449, 2025). "This is evidenced by the observed suppression of established hepatic fibrosis markers, including type I and IV collagen, TIMP-1, and MMPs (MMP-2 and MMP-9)." (PMID 39201682, 2024). "The study showed that betaine modulates the antifibrogenic effects of MIF in TAA-induced liver fibrosis, by decreasing TGF-β1, PDGF-BB, MMP-2, MMP-9, TIMP-1, and the deposition of ECM (Coll1 and Coll3) in the liver." (PMID 38927544, 2024). "Another study found that the injection of HSYA into Sprague Dawley rats regulated gene expressions of MMP-9 and TIMP-1 to reduce liver fibrosis in chronic liver disease." (PMID 39062816, 2024). "During the regression phase of liver fibrosis, MoMφs can participate in ECM degradation by secreting MMPs such as MMP9, MMP12, and MMP13, which facilitates the regression of liver fibrosis." (PMID 39635524, 2024). "MMP-9 played an important role in promoting the formation of NAFLD and the progression of liver fibrosis." (PMID 39064719, 2024). "The CRISPR-dCas9 system was used to activate the expression of endogenous MIAT, and the up-regulated MIAT significantly increased the hepatic fibrosis markers α-SMA, collagen I, and MMP9 of LX-2 and promoted cell proliferation." (PMID 37648688, 2023). "Conversely, TIMP1 was reduced, suggesting that the lost balance between MMP-9 and TIMP1 can contribute to the protective effects of SME against liver fibrosis." (PMID 38001866, 2023).
liver fibrosis (continued). "In CCl4-induced liver fibrosis, mRNA expression of MMP2 and MMP9 in the liver is elevated significantly." (PMID 37266145, 2023). "The reduction of hepatic inflammation correlated with a reduction in liver fibrosis and an increase in gelatinase MMPs (MMP-2 and MMP-9)." (PMID 37242695, 2023). "PI3K/AKT inhibition effectively attenuates MMP-9 expression induced by tumor necrosis factor-like weak inducer of apoptosis (TWEAK) and reduces ECM deposition, thereby delaying the development of liver fibrosis." (PMID 37513376, 2023). "In line with our finding that IF reduces hepatic LCN2, MMP9, and pSTAT3 expression in HFD-fed mice, LCN2 deletion and administration of a STAT3 phosphorylation inhibitor reduced inflammation and hepatic fibrosis." (PMID 37960230, 2023). "Animal experiments have shown that quercetin can ameliorate liver fibrosis by inhibiting HSCs activation and ECM formation and regulating COL1A1, COL3A1, MMP9, and TIMP1 mRNA expression levels." (PMID 35791909, 2022). "On the other hand, a study in mice with induced liver fibrosis reported increased MMP2 mRNA and decreased MMP9 mRNA." (PMID 36032279, 2022). "Several animal studies showed that melatonin decreased the expression levels for liver fibrosis markers TGF-β, MMP9, and TIMP1." (PMID 36077452, 2022). "The results revealed the reduced production of extracellular collagen by adjusting the balance of matrix metalloproteinase (MMP) 2, MMP9, and tissue inhibitor of matrix metalloproteinase 1 (TIMP1) in PZH-treated CCl4-induced liver fibrosis." (PMID 36188553, 2022). "Induction of liver fibrosis in rats using TAA for 6 weeks resulted in a significant elevation in hepatic contents of TGF-β1, α-SMA, collagen 1, and TIMP1 and reduced MMP9 content as compared to the normal group." (PMID 33628797, 2021). "More specifically, MMP‐9‐deficient mice have been reported to exhibit moderate protection against early fibrosis and proteolytic inactive MMP‐9 mutants, acting as TIMP‐1 antagonists in vitro and inhibiting CCl4‐induced liver fibrosis in mice." (PMID 34647412, 2021). "Matrix metalloproteinase-9 (MMP-9) specifically degrades type III collagen and gelatin to control the progression of liver fibrosis." (PMID 34055009, 2021). "MMP‐9 activates transforming growth factor (TGF‐β), a cytokine that enhances fibrogenesis, and it is also upregulated in liver fibrosis." (PMID 34647412, 2021). "Based on results of network pharmacology, it was known that flavonoids can possibly suppress liver fibrosis by inhibiting the IL-17 signaling pathway, which includes NF-κB, AP-1, IL-6, IL-1β, TNFα, IFN-γ, CCL2, COX2, MMP1, MMP3, and MMP9." (PMID 33551818, 2020). "Previous studies have shown that FIS supplementation prevents hepatic fibrosis by suppressing the gene expressions of COL1, MMP2, MMP3, and MMP9 and collagen accumulation." (PMID 33381023, 2020). "Several studies have shown that MMP2, one of the most studied enzymes in liver fibrosis, is mainly secreted by KCs and by HSCs while MMP-9 (gelatinase B) is predominantly expressed in KCs but can be also expressed by neutrophils, macrophages and fibroblasts." (PMID 32911524, 2020). "Reduction of liver fibrosis corroborates the results obtained by measurement of hepatic pro-fibrotic (TIMP-1, TGF-β1) and anti-fibrotic factors (MMP-9)." (PMID 31015492, 2019). "We further analyzed MMP-2, MMP-9, MMP-13 and tissue inhibitor of matrix metalloproteinases 1 (TIMP-1) hepatic gene expressions after BDL- and CCl-4-induced liver fibrosis using RT-PCR." (PMID 30875826, 2019). "In a rat model with bile duct ligation induced hepatic fibrosis, MMP-2 and MMP-9 activities has been demonstrated to increase within 2 days post ligation therefore, MMP-2 and MMP-9 are considered to be suitable markers for the onset of liver fibrosis." (PMID 31653214, 2019).
liver fibrosis (continued). "In comparison to that, the findings of this study show that PZQ appears to be effective in decreasing hepatic fibrosis, as demonstrated by a clear change in the hepatic expression of α-SMA, TGF-β1, TIMP-1, and MMP-9." (PMID 30273397, 2018). "The results indicated that ZLE has antifibrotic activity by reversing S. mansoni-induced liver fibrosis through reducing hepatic expression of TGF-β1, MMP-9, and TIMP-1 and increasing antioxidative status while limiting apoptosis." (PMID 30273397, 2018). "Since one of the major functions of HGF is the induction of matrix metalloproteases (MMPs), such as membrane type 1-MMP and MMP9 to degrade the extracellular matrix, a number of reports demonstrated the therapeutic effect of HGF in liver fibrosis." (PMID 30083132, 2018). "In a rat model of hepatic fibrosis induced by bile duct ligation (BDL), MMP-2 and MMP-9 were increased suggesting that continued tissue damage and inflammation induced MMP expression." (PMID 28086769, 2017). "It has been known that the expression levels of MMP2, MMP9, TIMP1 and TIMP2 mRNAs are increased in the patients with hepatic fibrosis." (PMID 26863419, 2016). "The results in the present study revealed that TWEAK promotes HSCs migration via canonical NF-κB/MMP9 pathway, which possibly provides a molecular basis targeting TWEAK for the therapy of liver fibrosis." (PMID 27907201, 2016). "In conclusion, MMP2, MMP9 and TNF-α showed high reproducibility to differentiate patients with liver fibrosis (F1–F4) from control group." (PMID 26464613, 2015). "MMP2, MMP9 and TNF-α showed a significant elevation in patients with liver fibrosis (F1–F4) compared to control group (p=0.001)." (PMID 26464613, 2015). "It has been shown that this catalytically inactive MMP-9 E402Q mutant binds TIMP-1 and neutralizes its effect in promoting liver fibrosis development." (PMID 25380300, 2014). "It is thought that the initial role of MMP-9 in liver fibrosis is the degradation of the normal basolateral matrix, and that subsequent decreases in ECM breakdown by MMP-9 lead to ECM accumulation and exacerbation of liver fibrosis." (PMID 21813019, 2011). "The initial investigation explored whether MO crude extract and OLA ameliorate hepatocyte injury and liver fibrosis on LX-2 cells by the analysis of cytokine and ECM production (IL-6, IL-8 and MMP-9)." (PMID 40244247, 2025). "Western blot analysis of liver fibrosis markers revealed that Huangqi Decoction significantly reduced the expression levels of alpha-smooth muscle actin (α-SMA), type I collagen, matrix metalloproteinase-2 (MMP-2), and matrix metalloproteinase-9 (MMP-9)." (PMID 39388703, 2025). "Moreover, S. mansoni-infected mice treated with Vilda and Vilda/DDS groups were comparable in hepatic fibrosis markers as TGF-β, α-SMA, and MMP-9 and showed higher significant reduction when compared to S. mansoni-infected mice treated with PZQ." (PMID 40128243, 2025). "Furthermore, IL-1β activates the HSC through matrix metallopeptidase 9 (MMP9), intensifying liver fibrosis." (PMID 40430529, 2025). "This study examined whether 3-HBI could reduce liver fibrosis in LX-2 cells by detecting its impact on the production of cytokines and the extracellular matrix (ECM) (IL-6, IL-8, and MMP-9)." (PMID 40649803, 2025). "Furthermore, Vilda/DDS modulated liver fibrosis through reduction of hepatic stellate cell activation through the inhibition of TGF-β, α-SMA, and MMP-9." (PMID 40128243, 2025). "In addition, MSCs upregulate MMPs (e.g., MMP9 and MMP13) and inhibit the expression of TIMPs (e.g., TIMP-1), which directly degrade ECM to alleviate liver fibrosis." (PMID 38360740, 2024). "Matrix metalloproteinase 9 (MMP9), an endopeptidase responsible for ECM component disruption and protein degradation, exhibited reduced expression in a previous study on Thioacetamide injection-induced liver fibrosis in rats." (PMID 38132319, 2023).
liver fibrosis (continued). "The enhanced generation and secretion of MMP-2 and some measure of MMP-9 after treatment with 5 μM CBG of hepatocytes exposed to palmitate and fructose solution might contribute to the reduction in experimental hepatic fibrosis." (PMID 37759466, 2023). "Additionally, MMP2, MMP3, and MMP9 are highly expressed during the acute phase of tissue damage, and the role of MMP12 in the treatment of mesenchymal stem cells for liver fibrosis has been reported." (PMID 37189708, 2023). "MMP-9 has been clearly shown to be of key importance in reversing liver fibrosis, but its exact mechanism of action has not yet been elucidated." (PMID 36232681, 2022). "In the liver fibrosis model, the expression of MMP-9 was higher than in the normal group, probably due to the synergy between MMP-9 and MMP-2 in restoring the structural integrity of liver cells and maintaining the normal morphology of the basement membrane of the liver sinusoids." (PMID 35883127, 2022). "HFFs treatment also could down-regulate the LN and PCIII of liver tissues, the indicators of liver fibrosis evaluated by ELISA and significantly decreased α-SMA, collagen I, TGF-β, TIMP1, and MMP9 expressions evaluated by Q-PCR, similar to UC-MSCs treatment." (PMID 35831878, 2022). "We further demonstrated that miR-6676-3p downregulated the mRNA expression of α-SMA, COLLAGEN I, TIMP1, TIMP3 and upregulated MMP2, MMP9, which are all profibrogenic genes in which TIMP1/3 antagonize MMP2/9 which decompose the collagen I during the progression of liver fibrosis." (PMID 34930304, 2021). "Since we show that external rigidity alone affects MMP-9 and TIMP-1 activity, we demonstrate the importance of mechanotransduction of high rigidities in liver fibrosis, in concurrence with studies that link the rigidity of the fibrotic liver to disease progression." (PMID 31086224, 2019). "Furthermore, the IGFBPrP1 knockdown attenuated liver fibrosis by re-establishing the MMP2/TIMP2 and MMP9/TIMP1 balance concomitant with the inhibition of HSCs activation and degradation of the ECM." (PMID 30769840, 2019). "Thus, the expression of many hepatic fibrosis markers such as Col1A1, FN1, MMP9 and TIMP1 was more abundant in GWI-BDL group than in naïve-BDL controls." (PMID 30177688, 2018). "Indeed, in the context of liver fibrosis, myeloid cells, including macrophages, neutrophils and dendritic cells are important sources of MMP-13 and MMP-9, respectively." (PMID 28118605, 2017). "Based on the fact that MMP-9 (gelatinase B) is one of fibrotic markers reported to be upregulated in liver fibrosis and is a major MMP in basement membrane-like ECM remodeling, we therefore determined whether TL extract can suppress MMP-9 activity." (PMID 29410686, 2017). "We investigated whether CA treatment would alter the expression of MMP9 (a class of enzymes that involved in the degradation of the ECM), as well as TGF-β1 and its receptor, TGF-β R1, in BDL-induced liver fibrosis." (PMID 29403377, 2017). "In this research, c-fos (a member of AP-1), P65 (a member of NF-κB), and TGF-β1 were increased markedly during the initiation of hepatic fibrosis, which might enhance the expression of MMP-2 and MMP-9." (PMID 27739503, 2016). "While TGFβ1 is increased in serum of patients with NASH and contributes to liver fibrosis secondary to NASH, the role of MMP-9 could apparently have a contradictory role." (PMID 25502575, 2014). "A CD11bhi/F4/80infLY6Clow macrophage subpopulation was identified during the resolution of liver fibrosis; these special cells do not produce fibrogenic and/or inflammatory factors, but they continue to secrete MMPs, including MMP9 and MMP12, and they upregulate CX3CR1." (PMID 39063116, 2024). "The ratio of MMP9/TIMP1 and MMP13/TIMP1 showed increments in the liver after chlorophyllin treatment, indicating that administration of chlorophyllin may promote the fibrolysis and resolving liver fibrosis." (PMID 30564133, 2018).
liver fibrosis (continued). "Interestingly, MMP9-immunopositive cells, irrespective of their origin from ES cells or the recipient, were immunopositive for DlK-1, a hepatoblast marker, suggesting that hepatoblast-like cells play an important role in the regression of liver fibrosis." (PMID 19134049, 2008). "We measured MMP-2, MMP-9, and their inhibitors (TIMP-1, TIMP-2) in the CCl4-induced liver fibrosis group with/without UCB-Exo treatment." (PMID 34772443, 2021). "In the current study, we found that a nonselective MMP inhibitor, MMP‐2/MMP‐9 inhibitor and MMP‐9 gene deletion consistently attenuated liver fibrosis in the BDL animal model." (PMID 34647412, 2021). "Thus current results suggested that MMP2, MMP9 and TNF-α could be considered as potential markers of inflammation but not of the degree of liver fibrosis in chronic HCV patients." (PMID 26464613, 2015).